RAB20 (RAB20, member RAS oncogene family)
Description:
The small GTPases Rab are key regulators of intracellular membrane trafficking, from the formation of transport vesicles to their fusion with membranes. Rabs cycle between an inactive GDP-bound form and an active GTP-bound form that is able to recruit to membranes different sets of downstream effectors directly responsible for vesicle formation, movement, tethering and fusion (By similarity). RAB20 plays a role in apical endocytosis/recycling. Plays a role in the maturation and acidification of phagosomes that engulf pathogens, such as S.aureus and M.tuberculosis. Plays a role in the fusion of phagosomes with lysosomes.
Synonyms: FLJ20429
Tractability: Antibody: its Gene Ontology location is reachable by antibodies, with medium confidence. PROTAC: ubiquitination databases record sites on it; its protein half-life has been measured.
Gene: Protein-coding gene on chromosome 13 (110,523,066 to 110,562,127, reverse strand). Ensembl gene ENSG00000139832.
Subcellular location: Golgi apparatus; Cytoplasmic vesicle, phagosome; Cytoplasmic vesicle, phagosome membrane
Subcellular location (Human Protein Atlas): Vesicles; Golgi apparatus
Pathways (Reactome):
Metabolism of proteins: RAB geranylgeranylation
Gene Ontology:
Molecular function: GTPase activity; G protein activity; GTP binding
Biological process: phagosome acidification; phagosome-lysosome fusion; endocytosis
Cellular component: Golgi apparatus; phagocytic vesicle; early endosome; endocytic vesicle; plasma membrane; phagocytic vesicle membrane
Genetic constraint (gnomAD): Loss-of-function variants: 4 observed, 4.66 expected, observed/expected ratio (o/e) 0.86, 90% interval 0.42 to 1.74. That is too few expected variants to judge how well the gene tolerates losing a copy. Missense variants: 276 observed, 321.73 expected, observed/expected ratio (o/e) 0.86, 90% interval 0.78 to 0.95. Synonymous variants: 126 observed, 135.72 expected, observed/expected ratio (o/e) 0.93, 90% interval 0.8 to 1.08.
Homologues: Orthologues: macaque RAB20 (97% identical), dog RAB20 (84% identical), mouse Rab20 (82% identical), pig RAB20 (82% identical), rat Rab20 (79% identical), guinea pig RAB20 (74% identical), tropical clawed frog rab20 (65% identical), zebrafish rab20 (65% identical), Caenorhabditis elegans C52B11.5 (21% identical). Paralogues in human: RAB5B (30% identical), RAB8B (30% identical), RAB17 (29% identical), RAB26 (29% identical), RAB5A (29% identical), RAB11A (29% identical), RAB11B (29% identical), RAB10 (28% identical), RAB1A (28% identical), RAB1B (28% identical), RAB36 (28% identical), RAB5C (28% identical), and 56 more.
Diseases named in the same sentence as RAB20 in open-access papers:
RAB20 is named in the same sentence as 43 diseases in open-access papers, as found by Europe PMC text mining. Sharing a sentence is not in itself a finding about the gene and the disease. The quoted sentences say what the papers report.
exocrine pancreatic carcinoma (4 papers, 2012 to 2020). "Less is known about RAB20 function, a Golgi-associated Rab overexpressed in exocrine pancreatic carcinoma." (PMID 22724020, 2012). "Rab20 is overexpressed in exocrine pancreatic carcinoma, and silencing of Rab20 reduced hypoxia-induced apoptosis." (PMID 25472813, 2015). "Furthermore, RAB20 gene expression is reported to be up-regulated during the acute phase of brain inflammation, in pancreatic tumour cell lines, and in primary pancreatic carcinomas." (PMID 23874396, 2013).
colorectal adenoma (3 papers, 2015 to 2022). An adenoma that arises from the colon or rectum. "Overexpression and amplification of RAB20 have been detected in pancreatic carcinoma, colorectal adenoma, and triple-negative breast cancer and are associated with high-risk clinicopathological stages and poor survival outcomes." (PMID 35267417, 2022). "RAB20 amplifications were strongly correlated with the presence of high-grade dysplastic colorectal adenomas, and aberrations of Rab20 were associated with high-risk colorectal adenomas." (PMID 32138279, 2020). "Moreover, RAB20 amplification was also correlated with high-grade dysplastic colorectal adenomas." (PMID 25693204, 2015).
hepatocellular carcinoma (3 papers, 2021 to 2025). A malignant tumor that arises from hepatocytes. "In hepatocellular carcinoma (HCC), using RNA sequencing comparing expression profiles of adjacent non‐tumorous tissues and HCC, Rab20 is identified to be the most frequently downregulated Rab member in HCC." (PMID 34401050, 2021). "However, in hepatocellular carcinoma (HCC), RAB20 is lowly expressed." (PMID 41153010, 2025).
pancreatic cancer (3 papers, 2020 to 2025). "RAB20 has been reported to be upregulated in colorectal cancer and pancreatic cancer, and the overexpression of RAB20 is associated with liver metastasis of colorectal cancer." (PMID 41153010, 2025).
tuberculosis (3 papers, 2017 to 2022). A chronic, recurrent infection caused by the bacterium Mycobacterium tuberculosis. "The decision tree identified INSL3 and RAB20 (Decision-tree genes) as the optimal gene set to classify tuberculosis status among patients from both sites." (PMID 33692804, 2021). "Rab20 is specifically and significantly upregulated in the sputum of human patients with active tuberculosis." (PMID 28494243, 2017).
asthma (2 papers, 2017). "A single nucleotide polymorphism (SNP) in RAB20 has been associated with childhood asthma in European-American and Hispanic-American populations using genome wide association study (GWAS)." (PMID 29231896, 2017). "Further supporting the role of Rab20 in immunity, analysis of gene expression in lungs in the mouse model of asthma showed an increase of Rab20 expression after injection with ovalbumin." (PMID 29034219, 2017).
colorectal cancer (2 papers, 2020 to 2025). A primary or metastatic malignant neoplasm that affects the colon or rectum. "Amplification of Rab20 was strongly correlated with adenoma recurrence and the presence of colorectal carcinomas, whereas overexpression of RAB20 was associated with colorectal carcinoma liver metastases." (PMID 32138279, 2020). "Since Ikaros’ role in macrophage function, colorectal cancer, and MDS was described previously, the data presented here suggested that Ikaros activity in these conditions might be mediated via regulation of RAB20 transcription." (PMID 32138279, 2020).
Crohn disease (2 papers, 2019 to 2022). A gastrointestinal disorder characterized by chronic inflammation involving all layers of the intestinal wall, noncaseating granulomas affecting the intestinal wall and regional lymph nodes, and transmural fibrosis. "Rab20’s expression was increased during B cell transformation by a polymorphism associated with Crohn’s disease and vaccination." (PMID 35706450, 2022).
triple-negative breast carcinoma (2 papers, 2020 to 2022). An invasive breast carcinoma which is negative for expression of estrogen receptor (ER), progesterone receptor (PR), and human epidermal growth factor receptor 2 (HER2). "In addition, the overexpression of RAB20 in triple-negative breast cancer has been associated with advanced disease stages and poor patient prognosis." (PMID 35267417, 2022). "Deregulation and a potential oncogenic role for Rab20 was reported in triple negative breast cancer and in bladder cancer." (PMID 32138279, 2020).
acute lymphoblastic leukemia (1 paper, 2020). Leukemia with an acute onset, characterized by the presence of lymphoblasts in the bone marrow and the peripheral blood. "The gain-of-function and loss-of-function experiments presented above demonstrated that Ikaros regulates expression of the RAB20 gene in B-cell acute lymphoblastic leukemia (B-ALL)." (PMID 32138279, 2020).
brain infarct (1 paper, 2022). "Rab20 inhibition significantly alleviated brain infarct volume, neurological deficits, and neuronal apoptosis in mice after I/R." (PMID 36385754, 2022).
brain inflammation (1 paper, 2017). "Supporting the idea that Rab20, together with Rab32, are part of a group of small GTPases linked to inflammation, the up-regulation of both Rab20 and Rab32 during the acute phase of LPS-induced brain inflammation has been reported." (PMID 29034219, 2017).
breast carcinoma (1 paper, 2015). "In particular, RAB20 expression is increased in exocrine pancreatic adenocarcinomas and in breast cancer." (PMID 25693204, 2015).
candidiasis (1 paper, 2021). Infection with the organism Candida. "Interestingly, we showed that genetic variation in close vicinity of the phagocytosis/phagosome maturation-associated genes ASGR2, LAMP1, RAB42, GEM, ATP6V1B2, and RAB20 are associated with susceptibility to candidiasis." (PMID 33510868, 2021).
Cerebral ischemia (1 paper, 2022). Restriction of arterial blood supply to the brain associated with insufficient oxygenation to support the metabolic requirements of the tissue. "However, the role and mechanism of Rab20 in cerebral ischemia/reperfusion (I/R) injury need to be elucidated." (PMID 36385754, 2022).
cerebral small vessel disease (1 paper, 2024). Cerebral small vessel disease is the term currently used to pathological processes that affect the brain parenchymal circulation (arterioles, capillaries, and veins). "For example, rs9515223 is a cis-eQTL in the COL4A2-AS1 RNA gene that has been associated with cerebral small vessel disease and decreased expression of COL4A2 and RAB20 in immune cells." (PMID 39530122, 2024).
COVID-19 (1 paper, 2023). A disease caused by infection with severe acute respiratory syndrome coronavirus 2. "For instance, IL1B, NFKB1, NLRP3, PYCARD, and CASP1 are listed in the COVID-19 Disease Map, while there are molecules absent from it, including CCL3, 3L1, 4L2, CXCL1, 2, 3, 5, 16, TNFAIP6, C15orf48, TMEM176A/B, NFE2, PADI4, RAB20, ETS2, PHLDA2, FOLR3, and HP." (PMID 37719701, 2023).
diabetic retinopathy (1 paper, 2020). "Reducing Rab20 expression could be a useful strategy in preventing HG-induced vascular and Müller cell death associated with diabetic retinopathy." (PMID 33227912, 2020). "Therefore, targeting Rab20 overexpression could be useful in improving cell–cell communication in retinal endothelial cells and Müller cells, and preventing neurovascular disruption associated with diabetic retinopathy." (PMID 33227912, 2020). "However, it is currently unknown whether intracellular trafficking of Cx43 is altered by HG via regulation of Rab20 and whether such changes influence cell survival in the context of diabetic retinopathy." (PMID 33227912, 2020). "Moreover, this aberrant Rab20 upregulation effectively inhibits Cx43 intracellular trafficking to the cell surface, thereby compromising GJIC activity and promoting loss of retinal endothelial cells and retinal Müller cells associated with diabetic retinopathy." (PMID 33227912, 2020).
glioblastoma (1 paper, 2019). The most malignant astrocytic tumor (WHO grade IV). "The increased expression of RAB20 found in the present study could suggest a role in macropinocytosis in glioblastoma." (PMID 30909495, 2019).
ischemic stroke (1 paper, 2022). A stroke disorder caused by obstruction of blood flow to the brain, due to thrombotic (local blood clot formation) or embolic (due to a blood clot or other material traveling from another site) event. "These important observations have promoted further exploration of the interaction between Rab20 and Drp-1 in mitochondrial fragmentation after ischemic stroke." (PMID 36385754, 2022). "Thus, Rab20 may promote mitochondrial fragmentation by inhibiting Drp-1 phosphorylation at Ser637, thereby inducing mitochondrial Drp1 recruitment and neuronal apoptosis after ischemic stroke." (PMID 36385754, 2022).
leukemia (1 paper, 2020). A malignant (clonal) hematologic disorder, involving hematopoietic stem cells and characterized by the presence of primitive or atypical myeloid or lymphoid cells in the bone marrow and the blood. "Demonstrating the involvement of the CK2–Ikaros axis in regulating RAB20 expression would represent a new class of genes, GTPases, regulated by Ikaros and provide insight into the cross-talk of signaling pathways in leukemia." (PMID 32138279, 2020). "In summary, the results presented in this manuscript identify a novel regulatory network in leukemia that involves CK2, PP1, Ikaros and the small GTPase Rab20." (PMID 32138279, 2020). "Here, we report that Ikaros regulates the expression of the small GTPase Rab20 in leukemia, and that CK2 and PP1 regulate Ikaros’ ability to repress RAB20 transcription." (PMID 32138279, 2020). "The potential role of Rab20 in leukemia is not well studied, although overexpression of RAB20 was observed in myelodysplastic syndrome." (PMID 32138279, 2020).
liver cancer (1 paper, 2021). An epithelial or non-epithelial malignant neoplasm that arises from the liver. "Rab20 downregulation was also shown in databases of liver cancer extracted from The Cancer Genome Atlas (TCGA) and Gene Expression Omnibus (GEO) platforms, suggesting that Rab20 downregulation was a common event in HCC pathogenesis." (PMID 34401050, 2021).
malaria (1 paper, 2012). Malaria is a serious and sometimes fatal disease caused by a parasite that commonly infects a certain type of mosquito which feeds on humans. "Therefore, the only two Rab GTPases that had their expression increased after incubation with both bacteria and the malaria parasite were Rab10 and Rab20." (PMID 22911692, 2012). "The results showed that, compared to the negative control, the live malaria parasite was able to induce an increase in the expression of Rab1a, Rab1b, Rab7a, Rab10, Rab14, Rab20, Rab27a, Rab32 and Rab38." (PMID 22911692, 2012).
mycoplasma infection (1 paper, 2020). "Expression of Rab20 in macrophages is positively regulated by the NF-κB pathway following mycoplasma infection, as well as by interferon-γ (IFN-γ) treatment, suggesting the role of Rab20 in immune activation of macrophages." (PMID 32138279, 2020).
Niemann-Pick disease type C (1 paper, 2009). NPC is a complex lipid storage disease mainly characterized by the accumulation of unesterified cholesterol in the late endosomal/lysosomal compartment. "Interestingly, a recent gene expression profiling comparison of normal and Niemann Pick disease type C (NPC) patient fibroblasts revealed changes in several genes important for membrane traffic including RAB20 and SorCS1." (PMID 19381295, 2009).
Obesity (1 paper, 2020). Accumulation of substantial excess body fat. "The response to CPAP therapy of CD1D and RAB20 suggests that the expression changes identified for these genes are due to OSA and not obesity." (PMID 32512511, 2020).
penile squamous cell carcinoma (1 paper, 2022). "Here, we performed comprehensive genomic sequencing on eight penile squamous cell carcinoma (PSCC) and normal tissue pairs and found that RAB20 was upregulated in tumors, especially in metastatic lymph nodes." (PMID 35267417, 2022).
pulmonary interstitial fibrosis (1 paper, 2022). "Next, we investigated the mechanisms by which RAB20 deficiency promotes pulmonary interstitial fibrosis and respiratory dysfunction in our model of silicosis." (PMID 36131930, 2022). "Together, these findings demonstrate that the RAB20 deficiency promotes silica crystal-induced pulmonary interstitial fibrosis and respiratory dysfunction, and establish a functional link between suppressed RAB20 expression and the susceptibility to silicosis." (PMID 36131930, 2022). "Moreover, the increased pulmonary interstitial fibrosis phenotype was associated with a decrease in dynamic compliance (Cdyn), tidal volume (TV), and minute volume (MV), and significantly increased respiratory resistance index (RI) in RAB20-deficient mice." (PMID 36131930, 2022). "This work establishes the critical role of RAB20 in preventing silica crystal-induced inflammatory responses and pulmonary interstitial fibrosis, a process that resembles the immunopathology of clinical silicosis." (PMID 36131930, 2022). "In the silicosis murine model, RAB20 knockout markedly enhanced the silica crystal-induced pulmonary interstitial fibrosis and respiratory dysfunction." (PMID 36131930, 2022).
rheumatoid arthritis (1 paper, 2022). A chronic, systemic autoimmune disorder characterized by inflammation in the synovial membranes and articular surfaces. "High Rab20 levels promote B cell activation and facilitate rheumatoid arthritis development." (PMID 35706450, 2022).
silicosis (1 paper, 2022). Silicosis is a respiratory disease caused by breathing in (inhaling) silica dust. "Together, these observations establish that RAB20 gene deficiency in lung monocytes/macrophages was strongly associated with the occurrence of silicosis." (PMID 36131930, 2022). "Taken together, this study provides a novel link between RAB20 deficiency and susceptibility of silicosis with implications for the prevention of this occupational disease." (PMID 36131930, 2022). "To test the functional relevance of RAB20 deficiency to the development of silicosis, we intratracheally injected a silica crystal suspension in wild-type (WT) mice and RAB20-deficient mice to establish a murine silicosis model." (PMID 36131930, 2022). "Knockout of RAB20 induced severe silicosis development by significantly promoting NLRP3 inflammasome activation and IL-1β release." (PMID 36131930, 2022). "We also confirmed this observation that RAB20 was notably lower in monocyte/macrophage cells from silicosis patients using real-time quantitative PCR." (PMID 36131930, 2022). "In addition, using a murine silicosis model, we show that the RAB20 knockout greatly promoted a crystalline silica-induced silicosis-like picture through enhancing the NLRP3 inflammasome activity and IL-1β release." (PMID 36131930, 2022). "This led to the finding that the decreased level of RAB20 in monocytes/macrophages may be strongly associated with NLRP3 inflammasome activation and the occurrence of silicosis." (PMID 36131930, 2022). "Notably, RAB20 deficiency was associated with significantly higher concentrations of IL-1β and slightly higher concentrations of IL-18 in the BALF when compared to WT mice established with silicosis." (PMID 36131930, 2022). "We performed single-cell sequencing in bronchoalveolar lavage fluid (BALF) from mine workers with silicosis and their co-workers who did not develop silicosis, and found that the RAB20 deficiency in monocytes/macrophages was strongly linked to the development of silicosis." (PMID 36131930, 2022).